HLF (HLF transcription factor, PAR bZIP family member)
Diseases named in the same sentence as HLF in open-access papers (continued):
Sharing a sentence is not in itself a finding about the gene and the disease.
liver fibrosis (3 papers, 2019 to 2022). "Our study disclosed the protective role miR-98 played in liver fibrosis by targeting HLF and regulating a novel HIF-1α/TGF-β/Smad2/3 signaling pathway." (PMID 32637414, 2020). "Further experiments demonstrated that miR-98 regulated liver fibrosis by targeting HLF directly and suppressing its expression." (PMID 32637414, 2020). "To determine the role of HLF in liver fibrosis, we detected the expression of α-SMA and HLF in LX-2 cells activated by TGF-β1." (PMID 32637414, 2020). "Our study indicated that the expression of HLF was high in liver tissues from patients with liver fibrosis." (PMID 32637414, 2020). "Collectively, our study demonstrates that miR-98 plays a pivotal role in liver fibrosis by targeting HLF signaling, which may be an effective therapeutic target." (PMID 32637414, 2020). "Our study found that miR-98 could suppress HLF expression in HSCs and attenuate liver fibrosis by inhibiting the HIF-1α/TGF-β/Smad2/3 axis." (PMID 32637414, 2020). "In addition, the expression levels of HLF were higher in liver tissues of patients with liver fibrosis than those in normal controls." (PMID 32637414, 2020). "Furthermore, miR-98 agomir alleviated hepatic fibrosis and inhibited HLF expression in mice." (PMID 32637414, 2020). "Xiang and others reported that IL-6 can be regulated by Hepatic leukemia factor (HLF) transcription and enhance the phosphorylation of STAT3, thus activating primary hepatic stellate cells and then aggravating hepatic fibrosis." (PMID 35462928, 2022). "Furthermore, the high expression of HLF was also detected in the fibrotic liver tissues from CCl4-, BDL-, and HFD-induced murine liver fibrosis." (PMID 32637414, 2020). "A previous study has shown that inactivation of HLF could inhibit HSC activation and alleviated liver fibrosis." (PMID 32637414, 2020). "Collectively, our study demonstrates that miR-98 suppress HSCs activation by targeting HLF directly and interacting with HIF-1α/TGF-β/Smad2/3 signaling pathway, which may be an effective therapeutic target for liver fibrosis." (PMID 32637414, 2020).
lung adenocarcinoma (3 papers, 2021 to 2026). A carcinoma that arises from the lung and is characterized by the presence of malignant glandular epithelial cells. "The fusion of human serum albumin with human lactoferrin (hLF-HSA) exerts strong anti-migratory effects in human lung adenocarcinoma cells through matrix metalloproteinase 1 (MMP1) downregulation." (PMID 41873731, 2026). "Here, we aimed to ascertain the anticancer activity of a novel rhLf that displays glycosylation profile comparable with the natural hLf, against human lung adenocarcinoma cells." (PMID 34748082, 2021). "This study showed the novel rhLf that resembles glycan structure of the natural hLf, exhibited the anticancer effects in human lung adenocarcinoma cells." (PMID 34748082, 2021).
Obesity (3 papers, 2014 to 2023). Accumulation of substantial excess body fat. "hLf administration might be a useful therapeutic target in obesity-associated adipose tissue dysfunction." (PMID 24571258, 2014). "ALPK3, HLF, FXN, and SPTAN1 are the only genes that have never been linked to obesity." (PMID 35677823, 2022).
Autoimmunity (2 papers, 2019 to 2023). The occurrence of an immune reaction against the organism's own cells or tissues. "Noteworthy, the considerable effects observed in our study not only confer relevance to hLF but also underline the importance of macrophage function in early-life development - marking this immune-subset a promising therapeutic target in the prevention of inflammation and autoimmunity in infants." (PMID 37868991, 2023).
endotoxemia (2 papers, 2017 to 2023). "Like bLf, protective activity against hypothermia has been described with hLf in mice underwent LPS-endotoxemia." (PMID 28257033, 2017). "Differential impact of concurrent, prophylactic, and therapeutic effects of intraperitoneal administration of hLf on endotoxemia were analyzed in mice by intravenous administration of LPS." (PMID 28257033, 2017). "In the model of mice endotoxemia, intraperitoneal administration of hLf provided protection against deleterious effects of LPS on the intestinal integrity." (PMID 28257033, 2017). "At intestinal level, neutralizing activity of bLf or hLf has been tested in models of endotoxemia in mice induced by the intraperitoneal administration of LPS." (PMID 28257033, 2017). "Protective action of hLf on the gut barrier function against the LPS-induced intestinal damage has also been described for hLf in in vitro cultures of Caco-2 cells and jejune segments of mice underwent LPS-endotoxemia." (PMID 28257033, 2017). "Modulatory effects of either hLf or bLf, including derived Lfcins, on parameters associated with inflammation, has been evidenced in models of intestinal and systemic-related endotoxemia induced by LPS (also known as endotoxin) from Gram-negative enterobacteria." (PMID 28257033, 2017). "The observed transcriptional response is also in line with evidence linking hLF-function to basal TLR-4 activation via its carbohydrate chains and suppression of TLR4 signaling upon endotoxemia through its peptide moiety." (PMID 37868991, 2023).
heart failure (2 papers, 2019 to 2025). Inability of the heart to pump blood at an adequate rate to meet tissue metabolic requirements. "A common variant in HLF associates with a decreased risk of heart failure, a lower risk of CAVB and RBBB, a smaller ventricle and a shorter QRS duration." (PMID 31641117, 2019). "In the cell model for heart failure progression, miR-103-3p has been shown to promote autophagy by targeting the hepatic leukemia factor (HLF) transcription factor as well as FYVE and coiled-coil domain autophagy adaptor 1 (FYCO1) that directly interact with LC3 to increase autophagic flux." (PMID 40823532, 2025).
Sepsis (2 papers, 2016 to 2017). Sepsis is defined as life-threatening organ dysfunction caused by a dysregulated host response to infection. "There have been two completed trials of human recombinant lactoferrin (hLF) for the treatment of sepsis." (PMID 27681799, 2016). "Treatment with r-hLf decreased the clinical sepsis illness and bacterial loads in the kidney and blood while in vitro assays in macrophage cultures showed that levels of nitric oxide, TNFα and NF-κB expression elicited by LPS were even higher following the addition of r-hLf." (PMID 28257033, 2017).
Allergy (1 paper, 2024). An allergy is an immune response or reaction to substances that are usually not harmful. "The current study identified that Helaina rhLF is a very pure protein with ≥99% of the protein content being the target protein, hLF, which is not linked with allergy." (PMID 39114650, 2024).
cardiac hypertrophy (1 paper, 2019). "The knockout of HLF along with two other PAR bZip transcription factors has been shown to lead to cardiac hypertrophy and left ventricular dysfunction in mice." (PMID 31641117, 2019).
clear cell renal cell carcinoma (1 paper, 2025). "Here, using clear cell renal cell carcinoma (ccRCC), a tumor type with frequent lung metastases, we conduct an in vivo genome-wide CRISPR-Cas9 screen and identify HLF as a potent suppressor of lung metastasis." (PMID 40473600, 2025).
colon carcinoma (1 paper, 2020). "The N-terminal portion of hLf, containing a unique cluster of four consecutive arginine residues (G1RRRR5), was demonstrated to be essential for hLf interaction with GAGs on the human colon carcinoma cell line HT29-18-C1 as well as on Jurkat human lymphoblastic T-cells." (PMID 32183434, 2020).
colorectal adenocarcinoma (1 paper, 2021). The most common type of colorectal carcinoma. "The cBioPortal database was used to analyze the mutations of seven genes, which showed that E2F3, ETS2, HLF, HSF4, KLF4, MEIS2, and TCF7L1 were altered in 8, 8, 6, 6, 5, 9, and 6% of 524 colorectal adenocarcinoma patients separately." (PMID 34603375, 2021).
colorectal cancer (1 paper, 2025). A primary or metastatic malignant neoplasm that affects the colon or rectum. "We observed that HLF overexpression inhibited 3D collagen invasion or transwell invasion in these cell lines in vitro, as well as decreased lung metastasis of colorectal carcinoma cell line HCT116 in vivo." (PMID 40473600, 2025).
colorectal polyps (1 paper, 2014). "The data presented in this report show a good correlation between increased levels of NK cell activity in the blood, increased levels of serum hLF, which reflects systemic neutrophil responsiveness, and regression of colorectal polyps." (PMID 24867408, 2014).
gallbladder cancer (1 paper, 2025). "Here, we reported that hepatic leukemia factor (HLF) was highly expressed in gallbladder cancer stem cells (CSCs) and patients with gemcitabine-resistant GBC." (PMID 40779629, 2025).
gout (1 paper, 2016). A condition characterized by painful swelling of the joints, which is caused by deposition of urate crystals. "A similar opposing direction of association between European and Polynesian is also evident at other urate- and gout-associated loci PRKAG2 and HLF." (PMID 26808548, 2016).
head and neck cancer (1 paper, 2020). A primary or metastatic malignant neoplasm affecting the head and neck. "This hLf effect was also reported in four models of head and neck cancer cells, which resulted arrested in G1 to S transition upon hLf treatment." (PMID 32183434, 2020).
Hepatic steatosis (1 paper, 2025). Steatosis is a term used to denote lipid accumulation within hepatocytes. "Study of the mechanism revealed that the HLF/PPARα axis regulated gut microbiota‐derived extracellular vesicles (fEVs); which, through the gut‐liver cycle, suppressed hepatocyte ferroptosis and reduced hepatic steatosis." (PMID 40236774, 2025).
Hepatitis (1 paper, 2017). Inflammation of the liver. "In the experimental scenario, r-hLf provided protection against hepatitis development as determined by the decrease in alanine transaminase activity as the marker of liver damage, which was associated with down-modulation of serum TNFα levels." (PMID 28257033, 2017). "Treatment with r-hLf has also been analyzed in the same mice models of induced hepatitis." (PMID 28257033, 2017).
idiopathic pulmonary fibrosis (1 paper, 2024). Idiopathic pulmonary fibrosis (IPF) is a nonneoplastic pulmonary disease that is characterized by the formation of scar tissue within the lungs in the absence of any known cause. "Further, the nuclear localization of miR-9 was confirmed by RNA fluorescence in situ hybridization (FISH) in MLg cells and hLF from control donors (Ctrl hLF) or patients with idiopathic pulmonary fibrosis (IPF hLF), a lethal interstitial lung disease involving TGFB1 signaling." (PMID 39706840, 2024).
kidney cancer (1 paper, 2025). Primary or metastatic malignant neoplasm involving the kidney. "We provide direct evidence that decreased HLF expression, caused by enhancer loss in metastatic kidney cancer cells, has functional consequences and directly contributes to the metastatic phenotype." (PMID 40473600, 2025).
metastatic cancers (1 paper, 2025). A carcinoma which has spread from the original site of growth to another anatomic site. "Our findings highlight the unique role of HLF in solid tumor metastasis through cell-matrix interactions, suggesting potential therapeutic strategies for targeting HLF in metastatic cancer." (PMID 40473600, 2025).
metastatic tumors (1 paper, 2025). "We found that HLF levels were lower in most metastatic tumors compared to primary tumors including kidney, liver, pancreas, prostate and skin cancers." (PMID 40473600, 2025). "Additionally, the upstream regulator of HLF, SMARCA4, exhibited higher expression in metastatic tumors compared to primary tumors across multiple cancer types." (PMID 40473600, 2025).
nasopharyngeal carcinoma (1 paper, 2021). A carcinoma arising from the nasopharyngeal epithelium. "Experiments with hLf demonstrated the further downregulation of 3-phosphoinositide-dependent protein kinase 1 (PDK1) transcription via mitogen-activated protein kinase/c-Jun pathway following deactivation of AKT signaling leading to inhibition of nasopharyngeal carcinoma (NPC) tumorigenesis." (PMID 34201342, 2021).
necrotizing enterocolitis (1 paper, 2025). Necrotizing enterocolitis (NEC) is a devastating disease that affects mostly the intestine of premature infants. "Hence, hLF and bLF are also used in studies to avoid necrotizing enterocolitis (NEC) in preterm infants." (PMID 40003872, 2025).
pancreatic cancer (1 paper, 2021). "Notably, this is the first study to show that HLF is closely associated with pancreatic cancer metastasis." (PMID 34485257, 2021). "Finally, HLF was the only down-regulated gene in the TCGA pancreatic cancer metastasis group." (PMID 34485257, 2021).
Parkinson disease (1 paper, 2021). A progressive degenerative disorder of the central nervous system characterized by loss of dopamine producing neurons in the substantia nigra and the presence of Lewy bodies in the substantia nigra and locus coeruleus. "We studied the effect of human lactoferrin (hLf) on degenerative changes in the nigrostriatal system and associated behavioral deficits in the animal model of Parkinson disease." (PMID 33401480, 2021).
preeclampsia (1 paper, 2018). Preeclampsia is a hypertensive disorder of pregnancy that is characterized by new-onset hypertension with proteinuria presenting after 20 weeks of gestation, and depending on mild or severe forms may initially present with severe headache, visual disturbances, and hyperreflexia. "Among transcription regulatory genes of module M1, HLF had strong down-regulation only in preterm preeclampsia while ZNF554 was expressed at a lower level in all preeclampsia phenotypes." (PMID 30135684, 2018).
renal cell carcinoma (1 paper, 2021). "Lower HLF expression was correlated with more advanced renal cell carcinoma (RCC) and HNSCC." (PMID 34970597, 2021).
sarcoidosis (1 paper, 2023). Sarcoidosis is a multisystemic disorder of unknown cause characterized by the formation of immune granulomas in involved organs. "We found that, unlike their control counterparts, both cardiac and BAL sarcoidosis T cells showed enrichment of memory T cell TF genes (RFX7 and ZEB1), survival and proliferation TF genes (HLF and HIST1H2BN) and type 3 response TF genes (ARNTL and ADARB1)." (PMID 37576111, 2023).
Stargardt disease (1 paper, 2022). "This study revealed that several ABCA4 variants found in patients with Stargardt disease could affect ABCA4 expression, and common variants of the ABCA4 proximal promoter alter the ABCA4 transcriptional activity, which is regulated by GATA-2 and HLF." (PMID 36566289, 2022).
thyroid carcinoma (1 paper, 2024). "Of the three genes, only HLF was of prognostic significance in the disease-free interval (DFI) of TCGA thyroid carcinoma (THCA) patients." (PMID 39872516, 2024).
tumor (50 papers, 2011 to 2025). "Tumor-associated macrophages can secrete transforming growth factor beta (TGF-β) to turn on hepatic leukemia factor (HLF), which enhances the transcription of gamma-glutamyltransferase 1 (GGT1) and promotes resistance to ferroptosis in TNBC." (PMID 39833180, 2025). "Cancer metastasis is a complex, multi-step process where HLF loss can influence both cancer cell dissemination from the primary tumor and localization at distant sites." (PMID 40473600, 2025). "HLF overexpression was positively associated with gallbladder stone, histological differentiation, lymph node metastasis, and tumor-nodes-metastasis stage, suggesting that it plays a vital role in GBC progression." (PMID 40779629, 2025). "In contrast, HLF expression level was closely associated with tumor progression." (PMID 40124619, 2025). "Similarly, in a mouse model of cervical carcinoma expressing hLF, impaired tumor growth was associated with an increase in CD4+ and CD8+ T lymphocytes in peripheral blood." (PMID 37111542, 2023). "As expected, ARL14 was significantly up-regulated in tumor samples, while ZDHHC11B and HLF were clearly down-regulated in tumor." (PMID 39901294, 2025). "Through the in vivo CRISPR screening and functional validation, we identified hepatic leukemia factor (HLF) as a critical regulator that suppresses tumor cell metastasis to the lungs by modulating the interaction between cancer cells and collagen." (PMID 40473600, 2025). "After Univariate COX regression analysis, the factors associated with progression-free survival in patients with LUAD were tumor stage, tumor size, proximal metastasis, distant metastasis, HLF expression, and the number of CTCs." (PMID 40124619, 2025). "It was observed that HLF expression inversely correlated with CD8+ T cell infiltration in human tumor clinical samples." (PMID 40779629, 2025). "HLF has been reported to be dysregulated in human tumors, functioning as an oncogene or tumor suppressor depending on the context." (PMID 40779629, 2025). "In our study, individual CTCs and CTC clusters were successfully captured, and their numbers were strongly correlated with tumor progression and inversely correlated with HLF expression in tumor tissues." (PMID 40124619, 2025). "A notable reduction in C12ORF49 expression was observed in tumors developed from C12ORF49 silencing HLF, indicating that the observed suppressive impact on tumor growth was a result of C12ORF49 silencing." (PMID 40240331, 2025). "In training set (TCGA), ZDHHC11B and HLF were significantly downregulated in tumor samples, whereas ARL14 was significantly upregulated (P < 0.05)." (PMID 39901294, 2025). "Patients with high HLF expression in tumor tissues showed longer survival, with a median survival of 55.2 months." (PMID 40124619, 2025). "Alleviation of these effects by systemic depletion of CD8+ T cells further supports the critical role of p-STAT3/HLF/TFEB transactivation–regulated PD-L1 expression in tumor immunogenicity." (PMID 40779629, 2025). "Limited prior studies have indicated that HLF can act either as an oncogene or as a tumor suppressor, depending on the context." (PMID 37709768, 2023). "For example, oral administration of hLF increased the numbers of tumor-infiltrating CD4+ and CD8+ T cells in a mouse model of head and neck squamous cell carcinoma." (PMID 37111542, 2023). "We presented a 3D vascularized tumor model that spontaneously sprouted capillaries toward the tumor spheroid with the help of controlled interstitial flow and hLF‐secreted factors." (PMID 35286780, 2022). "Generally, hLf and bLf have been shown to exert anti-cancer activity for both tumor prevention and treatment." (PMID 32183434, 2020). "Humanized mouse models would be needed for future investigation on anti-tumor effects of hLF in combination with M860 in vivo." (PMID 31600968, 2019).